RUNX1 (RUNX family transcription factor 1)
Description:
Forms the heterodimeric complex core-binding factor (CBF) with CBFB. RUNX members modulate the transcription of their target genes through recognizing the core consensus binding sequence 5'-TGTGGT-3', or very rarely, 5'-TGCGGT-3', within their regulatory regions via their runt domain, while CBFB is a non-DNA-binding regulatory subunit that allosterically enhances the sequence-specific DNA-binding capacity of RUNX. The heterodimers bind to the core site of a number of enhancers and promoters, including murine leukemia virus, polyomavirus enhancer, T-cell receptor enhancers, LCK, IL3 and GM-CSF promoters (Probable). Essential for the development of normal hematopoiesis. Acts synergistically with ELF4 to transactivate the IL-3 promoter and with ELF2 to transactivate the BLK promoter. Inhibits KAT6B-dependent transcriptional activation (By similarity). Involved in lineage commitment of immature T cell precursors. CBF complexes repress ZBTB7B transcription factor during cytotoxic (CD8+) T cell development. They bind to RUNX-binding sequence within the ZBTB7B locus acting as transcriptional silencer and allowing for cytotoxic T cell differentiation. CBF complexes binding to the transcriptional silencer is essential for recruitment of nuclear protein complexes that catalyze epigenetic modifications to establish epigenetic ZBTB7B silencing (By similarity). Controls the anergy and suppressive function of regulatory T-cells (Treg) by associating with FOXP3. Activates the expression of IL2 and IFNG and down-regulates the expression of TNFRSF18, IL2RA and CTLA4, in conventional T-cells. Positively regulates the expression of RORC in T-helper 17 cells (By similarity). Isoform AML-1G shows higher binding activities for target genes and binds TCR-beta-E2 and RAG-1 target site with threefold higher affinity than other isoforms. It is less effective in the context of neutrophil terminal differentiation. Isoform AML-1L interferes with the transactivation activity of RUNX1.
Synonyms: AML1; CBFA2; PEBP2A2; AMLCR1; AML1-EVI-1; CBF2alpha; EVI-1; PEBP2aB; PEBP2alpha; LOC100506403
Tractability: Small molecule: a high-quality ligand is known; it has a high-quality binding pocket. PROTAC: ubiquitination databases record sites on it; its protein half-life has been measured; a small molecule that binds it is known.
Target class: Transcription factor
Gene: Protein-coding gene on chromosome 21 (34,787,801 to 36,004,667, reverse strand). Ensembl gene ENSG00000159216.
Subcellular location: Nucleus
Subcellular location (Human Protein Atlas): Nucleoplasm; Vesicles
Pathways (Reactome):
Gene expression (Transcription): RUNX1 and FOXP3 control the development of regulatory T lymphocytes (Tregs); RUNX1 interacts with co-factors whose precise effect on RUNX1 targets is not known; RUNX1 regulates estrogen receptor mediated transcription; RUNX1 regulates expression of components of tight junctions; RUNX1 regulates genes involved in megakaryocyte differentiation and platelet function; RUNX1 regulates transcription of genes involved in BCR signaling; RUNX1 regulates transcription of genes involved in WNT signaling; RUNX1 regulates transcription of genes involved in differentiation of HSCs; RUNX1 regulates transcription of genes involved in differentiation of keratinocytes; RUNX1 regulates transcription of genes involved in differentiation of myeloid cells; RUNX1 regulates transcription of genes involved in interleukin signaling; RUNX2 regulates genes involved in differentiation of myeloid cells; RUNX3 regulates RUNX1-mediated transcription; RUNX3 regulates p14-ARF; Regulation of RUNX1 Expression and Activity
Developmental Biology: Differentiation of naive CD4+ T cells to T helper 1 cells (Th1 cells); Transcriptional regulation of granulopoiesis
Signal Transduction: Estrogen-dependent gene expression; Pre-NOTCH Transcription and Translation
Disease: SARS-CoV-1 activates/modulates innate immune responses
Transport of small molecules: SLC-mediated transport of organic cations
Gene Ontology:
Molecular function: DNA-binding transcription activator activity, RNA polymerase II-specific; protein binding; RNA polymerase II cis-regulatory region sequence-specific DNA binding; RNA polymerase II transcription regulatory region sequence-specific DNA binding; transcription cis-regulatory region binding; DNA-binding transcription factor activity, RNA polymerase II-specific; ATP binding; DNA binding; DNA-binding transcription factor activity; sequence-specific double-stranded DNA binding
Biological process: hemopoiesis; myeloid leukocyte differentiation; positive regulation of DNA-templated transcription; positive regulation of granulocyte differentiation; positive regulation of interleukin-2 production; positive regulation of transcription by RNA polymerase II; regulation of transcription by RNA polymerase II; cardiac muscle tissue regeneration; chondrocyte differentiation; hematopoietic stem cell proliferation; negative regulation of CD4-positive, alpha-beta T cell differentiation; negative regulation of transcription by RNA polymerase II; neuron differentiation; ossification; peripheral nervous system neuron development; positive regulation of angiogenesis; positive regulation of CD8-positive, alpha-beta T cell differentiation; positive regulation of collagen biosynthetic process; positive regulation of extracellular matrix organization; regulation of cardiac muscle cell proliferation; regulation of cell differentiation; regulation of connective tissue replacement; regulation of plasminogen activation; positive regulation of developmental process; positive regulation of multicellular organismal process; and 2 more
Cellular component: core-binding factor complex; nucleoplasm; nucleus; chromatin
Genetic constraint (gnomAD): Loss-of-function variants: 15 observed, 36.49 expected, observed/expected ratio (o/e) 0.41, 90% interval 0.27 to 0.63. The upper end of that interval is the gene's LOEUF score, 0.63, which puts it in group 2 of 6, group 1 being the genes least tolerant of losing a copy. Missense variants: 508 observed, 608.31 expected, observed/expected ratio (o/e) 0.84, 90% interval 0.78 to 0.9. Synonymous variants: 269 observed, 254.27 expected, observed/expected ratio (o/e) 1.06, 90% interval 0.96 to 1.17.
Gene-disease validity (ClinGen):
ClinGen rates the evidence that RUNX1 causes each of these diseases.
hereditary thrombocytopenia and hematologic cancer predisposition syndrome (autosomal dominant): Definitive. The disorder is characterized by thrombocytopenia of varying severity and a predisposition to hematologic malignancies.
Cancer hallmarks: invasion and metastasis (promotes); angiogenesis (suppresses); proliferative signalling; change of cellular energetics (promotes); escaping programmed cell death (suppresses); tumour promoting inflammation (suppresses); suppression of growth (promotes); proliferative signalling (promotes); genome instability and mutations (suppresses); escaping programmed cell death (promotes); invasion and metastasis (suppresses); escaping immune response to cancer; genome instability and mutations
Homologues: Orthologues: chimpanzee RUNX1 (100% identical), macaque RUNX1 (99% identical), dog RUNX1 (99% identical), pig RUNX1 (98% identical), rabbit RUNX1 (96% identical), guinea pig RUNX1 (95% identical), mouse Runx1 (93% identical), rat Runx1 (90% identical), tropical clawed frog runx1 (84% identical), zebrafish runx1 (70% identical), Drosophila melanogaster lz (37% identical). Paralogues in human: RUNX2 (64% identical), RUNX3 (56% identical).
Diseases named in the same sentence as RUNX1 in open-access papers:
RUNX1 is named in the same sentence as 433 diseases in open-access papers, as found by Europe PMC text mining. Sharing a sentence is not in itself a finding about the gene and the disease. The quoted sentences say what the papers report.
leukemia (625 papers, 2002 to 2026). A malignant (clonal) hematologic disorder, involving hematopoietic stem cells and characterized by the presence of primitive or atypical myeloid or lymphoid cells in the bone marrow and the blood. "Runt-related Transcription Factor 1 (RUNX1) is essential for definitive hematopoiesis and is among the most frequently mutated genes in leukemia." (PMID 41214140, 2026). "Leukemia is a cancer affecting blood and bone marrow cells, often caused by mutations involving key hematopoietic transcription factors, such as Runt-related transcription factor 1 (RUNX1, also known as AML1)." (PMID 41214140, 2026). "This alteration generates the ETV6::RUNX1 (E::R) fusion gene, encoding an aberrant transcription factor that is insufficient to directly cause leukemia, but establishes a clinically silent pre-leukemic progenitor not yet fully characterized." (PMID 41813667, 2026). "Off-targeting activity of RAG enzymes drives the secondary mutational processes in ETV6::RUNX1 leukemia, causing SVs for example at TBL1XR1 locus, which is associated with inferior outcome." (PMID 40634509, 2025). "This suggests that Cbfb-MYH11–expressing cells with one allele of RUNX1-R188Q are still able to generate the pre-leukemic AMPs but fail to progress to full-blown leukemia." (PMID 40763310, 2025). "The leukemia fusion gene CBFB-MYH11 requires RUNX1 for leukemogenesis, but the underlying mechanism is unclear." (PMID 40763310, 2025). "In summary, we integrated multiomic data with treatment response profiles to characterize the genetic alterations and biological processes associated with therapy response in pediatric ETV6::RUNX1 leukemia." (PMID 40634509, 2025). "RUNX1 mutations are consistently associated with a poor prognosis, contributing to lower rates of complete remission (CR), leukemia-free survival (LFS), and overall survival (OS) compared to wild-type RUNX1 AML." (PMID 40558237, 2025). "For example, DCC is a well-characterized human colorectal cancer suppressor gene, and RUNX1 mutations are closely related to tumorigenesis in human leukemia and breast cancer." (PMID 40833781, 2025). "It is reported that AML with RUNX1 mutations is associated with poorer response to conventional chemotherapy, lower rates of complete remission (CR), leukemia-free survival (LFS), and overall survival (OS)." (PMID 40558237, 2025). "Studies in twins and mouse models have demonstrated that ETV6::RUNX1 establishes a preleukemic clone that can persist for years before acquiring secondary mutations that lead to overt leukemia." (PMID 40277842, 2025). "RUNX1 somatic mutations and chromosomal rearrangements are frequently observed in myelodysplastic syndrome and leukemias of myeloid and lymphoid lineages (i.e., AML, ALL, and CML)." (PMID 40519271, 2025). "In this study, we sought to evaluate the potential for mutations associated with the initiation of leukemia to perturb adenovirus infection by examining the impact of RUNX1 leukemic fusion genes on adenovirus persistence in B lymphocytic cells." (PMID 41497616, 2025). "Previous WGS analysis of ETV6::RUNX1 leukemias established a key role for the RAG-driven mutational process in the generation of SV at off-target sites." (PMID 40634509, 2025). "This study identified prenatal exposure to corticosteroids as a potential risk factor for prenatal ETV6::RUNX1 fusions and, thus, for leukemia development later in life." (PMID 40243620, 2025). "Ongoing research is focused on understanding resistance mechanisms to IDH inhibitors, as leukemia stemness and co-occurring mutations, such as RUNX1 and RAS-RTK pathway alterations, can drive resistance to these targeted therapies." (PMID 40277842, 2025). "In contrast, other genomic abnormalities, including mutations in FLT3, NRAS, and RUNX1, tend to be acquired later during leukemia development." (PMID 39590121, 2024).
leukemia (continued). "Mga deficiency in RUNX1::RUNX1T1 9 A expressing cells led to a significantly shortened leukemia latency with a median survival of 177 days for controls, 146 days for Mga(±) mice, and 132 days for Mga(−/−) mice." (PMID 38454121, 2024). "This was tested using an established murine leukemia model using retroviral expression of RUNX1::RUNX1T1 9a, which encodes a shortened form of RUNX1::RUNX1T1, that induces the rapid development of AML." (PMID 38454121, 2024). "Runx1-deficient mice die before birth from bleeding in the brain and blood system failure, and RUNX1 is closely linked to leukemia and myelodysplasia in human." (PMID 39822248, 2024). "For instance, RUNX1, including its mutations, has been reported to serve as a prognostic factor in tumors including leukemia, myeloid neoplasia, and renal cancer." (PMID 39822248, 2024). "The expansion of genetic explorations in leukaemia leads to the discovery of new germline RUNX1 variants." (PMID 36819173, 2023). "RUNX1 is frequently mutated in human leukemia patients, and the mutated protein is involved in leukemogenesis through a dominant‐negative effect on the normal RUNX1." (PMID 37489294, 2023). "Due to chromosomal translocations and point mutations, the AML1/RUNX1 gene (RUNX1) is one of the most frequently uncontrolled genes in leukemia." (PMID 37569414, 2023). "In this study, we add 10 families with germline RUNX1 variant explored at Armand Trousseau Hospital for leukaemia diagnosis or thrombocytopenia, to the 259 described so far." (PMID 36819173, 2023). "For example, upregulation of FOXO1 in AML with a RUNX1 mutation has been reported to help the growth of leukemia cells and inhibit the differentiation of CD34 + hematopoietic stem and progenitor cells." (PMID 38007419, 2023). "RUNX1 is one of the most frequently mutated gene in a variety of hematological malignancies and plays a tumor suppressor role in leukemia." (PMID 37760803, 2023). "Disease-initiating mutations in the transcription factor RUNX1 occur as germline and somatic events that cause leukemias with particularly poor prognosis." (PMID 37581927, 2023). "It is likely that additional cooperating lesions that can overcome the proliferative deficits associated with RUNX1::ERG are required to induce full-blown leukemia." (PMID 37002311, 2023). "We also found a strong association between the leukemia EV proteome and processes associated with the transcription factor RUNX1, whose mutation has been shown to play an important role in the development of hematological malignancies." (PMID 37986165, 2023). "Here, we described 10 French families with germline RUNX1 variants, explored at Armand Trousseau Hospital for leukaemia diagnosis or thrombocytopenia, with detailed description of personal and family history of haematological pathologies." (PMID 36819173, 2023). "The presence of STAG2, SRSF2 and RUNX1 mutations, alone or in combination, shortening both the time to leukemia transformation and the OS within MDS patients with isolated +8." (PMID 37568638, 2023). "As previously discussed in section "RUNX1 in DS-associated leukemia.", the implications of RUNX1 in Trisomy 21 have been mostly studied in the context of hematological malignancies." (PMID 37670378, 2023). "As a protein coding gene, diseases associated with RUNX1 include platelet disorder, myeloid malignancy and leukemia." (PMID 37927796, 2023). "Further, co-expression of full-length RUNX1::RUNX1T1 with activated c-KIT mutations efficiently triggered leukemia in vivo upon transplantation of transduced murine HSPCs into mice." (PMID 38201282, 2023). "The RUNX1–ETO fusion protein, which is found in t(8:21) leukemia and functions as a dominant negative form against wild-type RUNX1, was shown to cause the downregulation of eight genes involved in BER." (PMID 36672189, 2023).
leukemia (continued). "RUNX1 is primarily involved in normal hematopoiesis, and its mutation and gene translocation are critical causative factors for leukemia and other malignancy hematological diseases." (PMID 37697370, 2023). "Runt-related transcription factor 1 (RUNX1) is oncogenic in diverse types of leukemia and epithelial cancers where its expression is associated with poor prognosis." (PMID 37213235, 2023). "We compared the frequencies of SVs detected by OGM between the 2 genetic subgroups of BCP-ALL (ETV6::RUNX1+ and HD leukemia, n = 30 each) that occurred in addition to their hallmark events." (PMID 37469802, 2023). "RUNX1 was first identified in cancer by highly correlating the pathogenesis of leukemia disease with RUNX1 gene chromosome heterotopic and mutations." (PMID 38057816, 2023). "Much work has been undertaken in the paradigmatic pre-leukemia initiated in utero by the ETV6::RUNX1 gene fusion, the commonest single genetic cause of childhood BCP-ALL." (PMID 36959797, 2023). "In the recent ELN-recommendation, RUNX1 mutation was stated as a late event in leukaemia development, which contradicts earlier studies, considering RUNX1 mutations as early events in leukemognenesis." (PMID 37188777, 2023). "Third, in FA patients progressing from MDS to leukemia, cryptic RUNX1 lesions (translocations, deletions, or mutations) were observed." (PMID 37190015, 2023). "A recent study further showed that a frameshift variant of UBA2 was discussed to predispose to ETV6::RUNX1+ leukemia in monozygotic twins." (PMID 37469802, 2023). "For example, RUNX1 is necessary for normal hematopoietic production, and genetic alterations in the RUNX1 gene have been linked to various forms of leukemia and other hematological malignancies." (PMID 37760803, 2023). "We further identified well-known large recurrent 12p deletions (≥5 Mb) in ETV6::RUNX1 leukemia, which are associated with biallelic inactivation of the ETV6 gene." (PMID 37469802, 2023). "It is worth mentioning that secondary mutations in TBL1XR1 have recently been implicated in improving risk stratification, especially in ETV6::RUNX1 leukemia, where mutations led to inferior survival." (PMID 37469802, 2023). "The RUNX gene family is intimately involved in carcinogenesis: the RUNX1 gene was found to be mutated in human leukemia; and RUNX2 is overexpressed in osteosarcoma and regulates bone remodeling and osteoclast differentiation." (PMID 35522574, 2022). "The roles of RUNX1 in normal haematopoiesis are juxtaposed with high frequencies of RUNX1 mutations and translocations in leukaemia." (PMID 36467848, 2022). "In fact, chromosomal alterations as well as point mutations affecting AML1/RUNX1 gene have been observed in human leukemia, and patients with AML1 mutations exhibited poor clinical outcomes, underlying the important role of RUNX1 during hematopoiesis." (PMID 35884618, 2022). "RUNX1 has been associated with leukemia and solid tumor development in the skin, lung, intestine, and breast, while RUNX2 has been associated with osteosarcoma, thyroid carcinoma, as well as breast and prostate cancers." (PMID 36231060, 2022). "Presently, we lack information about somatic variants that drive progression to overt leukemia that, moreover, predict malignancy risk for individual RUNX1-FPD patients." (PMID 35884491, 2022). "The loss of RUNX1 function disturbs the differentiation of myeloid and lymphoid lines, which often leads to the development of leukemia." (PMID 36005134, 2022). "For instance, RUNX1 is required for normal hematopoiesis, and genetic alterations of the RUNX1 gene have been linked to various forms of leukemia and other hematological malignancies." (PMID 36430923, 2022).